RNU6-612P (RNA, U6 small nuclear 612, pseudogene)
Gene: Small nuclear RNA gene on chromosome 2 (60,719,640 to 60,719,741, forward strand). Ensembl gene ENSG00000252718.
Homologues: Orthologues: dog U6 (77% identical), rabbit U6 (77% identical), rat LOC120095355 (73% identical). Paralogues in human: RNU6-1331P (85% identical), RNU6-639P (83% identical), RNU6-1145P (82% identical), RNU6-1329P (82% identical), RNU6-38P (82% identical), RNU6-43P (82% identical), RNU6-590P (82% identical), RNU6-605P (82% identical), RNU6-727P (82% identical), RNU6-774P (82% identical), RNU6-1209P (81% identical), RNU6-1316P (81% identical), and 1286 more.